Y_RNA (Y RNA )
Gene: Miscellaneous RNA gene on chromosome 12 (100,257,688 to 100,257,790, reverse strand). Ensembl gene ENSG00000206790.
Homologues: Orthologues: chimpanzee Y_RNA (98% identical), macaque Y_RNA (96% identical), dog Y_RNA (85% identical), tropical clawed frog Y_RNA (78% identical). Paralogues in human: Y_RNA (93% identical), RNY3 (92% identical), Y_RNA (92% identical), Y_RNA (91% identical), Y_RNA (90% identical), RNY3P1 (89% identical), Y_RNA (89% identical), Y_RNA (88% identical), RNY3P16 (87% identical), RNY3P4 (87% identical), RNY3P9 (87% identical), Y_RNA (87% identical), and 96 more.